CRP (C-reactive protein)
Diseases named in the same sentence as CRP in open-access papers (continued):
Sharing a sentence is not in itself a finding about the gene and the disease.
schizophrenia (continued). "If this strategy is successful, CRP could be regarded as a first theranostic biomarker for tailoring anti-inflammatory/immune-modulating treatment to patients with schizophrenia, which could pave a way for more sophisticated markers in the future." (PMID 30766494, 2018). "Overall, these results in relation to CRP levels and cortical thickness provide further support for the role of inflammatory processes especially influencing prefrontal brain structure and cognition in patients with schizophrenia." (PMID 30364161, 2018). "Our finding of a correlation between CRP and negative symptoms is also interesting given the overlap of negative symptoms with cognitive symptoms, and a relatively consistent finding in several studies is that higher CRP correlates with worse cognitive function in schizophrenia." (PMID 29404313, 2017). "Elevated levels of the acute phase reactant C-reactive protein (CRP) have been observed in schizophrenia, yet relatively few studies have investigated the association between this inflammatory biomarker and psychotic symptoms in schizophrenia." (PMID 29404313, 2017). "One individual developed schizophrenia within one year of baseline assessment for CRP." (PMID 27622678, 2017). "A significant amount of evidence suggests that inflammation is a contributing factor to the pathophysiology of schizophrenia, and in agreement, changes in immunological markers have been found in blood, such as C-reactive protein (CRP) or different interleukins (IL) of patients with schizophrenia." (PMID 28358316, 2017). "Our findings correlating CRP with psychopathology support and contribute to the hypothesized influence of systemic inflammation upon psychosis in schizophrenia." (PMID 29404313, 2017). "Using CRP as a continuous measure, the OR for schizophrenia at age 27 years for each SD increase in CRP level at age 15/16 years was 1.22 (95% CI, 1.05–1.42), which remained significant after adjusting for potential confounders; adjusted OR 1.25 (95% CI, 1.07–1.46); P = 0.004." (PMID 27622678, 2017). "Further analysis after excluding two participants with very early age of onset still indicated a negative correlation between CRP levels and age of onset of schizophrenia; however, the strength of the association was reduced (rs = −0.28; P = 0.23)." (PMID 27622678, 2017). "Furthermore, a negative correlation has been observed between several systemic inflammatory markers, including CRP, and general cognitive functioning as well as with all facets of working memory in patients with schizophrenia." (PMID 29404313, 2017). "Based on the research carried out so far on the potential associations between CRP and specific psychotic domains of schizophrenia, no definite conclusions can be drawn and further exploration of this topic is needed." (PMID 29404313, 2017). "More specifically, higher CRP levels are shown to be associated with the severity of schizophrenia symptoms evaluated by the Positive and Negative Syndrome Scale (PANSS)." (PMID 28358316, 2017). "The researchers report that a genetically increased CRP level was significantly associated with a reduced risk of schizophrenia (a significant association is one unlikely to have arisen by chance)." (PMID 27327646, 2016). "Strikingly, as opposed to the current literature and previous inconclusive small-scale studies, our findings suggest that genetically elevated levels of CRP are not predisposing but in fact protective for schizophrenia." (PMID 27327646, 2016). "Notably, the leave-one-out sensitivity analysis revealed that the genetic overlap between CRP level and schizophrenia we observed at genome-wide and 1×10−4 significance thresholds was not driven by a few major SNPs." (PMID 27327646, 2016).
schizophrenia (continued). "We showed that elevated CRP levels driven by genetic factors are causally associated with protection against schizophrenia, suggesting that CRP may be one important puzzle piece that leads to an improved understanding of the pathogenesis of schizophrenia." (PMID 27327646, 2016). "For example, we found that high CRP is a biomarker of schizophrenia, MDD, and cancer." (PMID 27240929, 2016). "To ensure that the association between risk alleles for CRP and schizophrenia was not driven by a small number of genome-wide significant SNPs, we performed a leave-one-out sensitivity analysis of the 18 genome-wide SNPs." (PMID 27327646, 2016). "Among the 256 patients with schizophrenia, 100 (39.06%) had a high CRP level." (PMID 26041435, 2015). "C-reactive protein levels were significantly higher in the schizophrenia group." (PMID 27336034, 2015). "It should be noted that elevated levels of CRP has been observed in patients with BD and schizophrenia which may suggest an inflammatory component in these psychiatric illnesses." (PMID 23351198, 2012). "In patients with neuropsychiatric disorders such as schizophrenia and bipolar disorder, a lower cortisol/CRP ratio (interpreted as dysregulated HPA-immune balance) is associated with worse cognitive performance and more severe symptomatology, particularly in patients with schizophrenia." (PMID 41373439, 2025). "Moreover, the inflammatory hypothesis of schizophrenia gains support from studies that demonstrate synergistic effects of HSV-1 seropositivity and increased CRP levels regarding the degree of cognitive dysfunction observed in patients with schizophrenia." (PMID 40806558, 2025). "Furthermore, we discussed the link between schizophrenia and elevated pro-inflammatory factors such as CRP and NLR, emphasizing the broader implications of our findings for understanding the relationship between cannabis use, immune function, and mental health." (PMID 39502297, 2024). "Magnetic resonance imaging findings in schizophrenia relating to cardiac concentricity as a predictor of cardiovascular disease show evidence of adipose dysfunction; adiponectin is reduced, together with elevated levels of triglycerides, C-reactive protein, and fasting glucose." (PMID 39334950, 2024). "Furthermore, research on first-episode schizophrenia also indicated immune abnormalities in the patient’s peripheral blood, such as increased lymphocytes and inflammatory markers, including cytokines and C-reactive protein (CRP)." (PMID 39290303, 2024). "Interestingly, however, several MR studies have successively reported that genetically predicted higher level of CRP may be a protective factor of schizophrenia." (PMID 37076806, 2023). "Furthermore, the mitochondrial lymphocyte counts of CD3+ T and CD3+CD4+ T cells, as well as CRP levels, were positively correlated with BMI in schizophrenia patients, but the mitochondrial lymphocyte counts of CD3+CD4+ T cells were negatively correlated with the language scale in the RBANS." (PMID 38235140, 2023). "However, contrary to these beliefs, a large meta-analysis has revealed that CRP might have a protective effect against schizophrenia." (PMID 37600668, 2023). "Further, plasma levels of the acute phase protein C-reactive protein (CRP) are inversely correlated with prefrontal cortex (PFC) thickness in schizophrenia, which might suggest that the PFC is a brain region particularly vulnerable to peripherally derived inflammatory insult." (PMID 35027554, 2022). "In contrast to the use of antipsychotics, the elevated level of CRP in various human diseases has been decreased by using prebiotics, showing their potential as an alternative anti-inflammatory therapeutic agent to attenuate symptoms that cannot be controlled by medication in schizophrenia." (PMID 35269766, 2022).
schizophrenia (continued). "Moreover, we have shown that stratifying patients based on levels of IL-1β mRNA and CRP in the blood reveals some aspects of NF-κB dysregulation that are common to all people with schizophrenia and others that are unique to people with schizophrenia with inflammation." (PMID 35027554, 2022). "Moreover, resistance to the treatment of schizophrenia is correlated with high levels of CRP." (PMID 35269952, 2022). "The baseline levels of interleukin-6, CRP and leptin predicted incident MetS in schizophrenia patients, and it has been suggested that patients at increased risk of suffering the cardiometabolic adverse effects of antipsychotics could be identified before treatment initiation." (PMID 35794221, 2022). "Furthermore, the findings showed an increased serum level of CRP may also be used to predict the onset of schizophrenia along with various cognitive and physical complications of schizophrenia." (PMID 34884840, 2021). "Therefore, it is unclear whether CRP levels and kynurenic acid levels act as two independent markers occurring coincidentally during schizophrenia or have a complex interaction that leads to a possible cause–effect relationship." (PMID 34884840, 2021). "Using bidirectional MR analysis, the authors report that CRP could be causally linked with schizophrenia (elevated CRP level decreases risk), but schizophrenia is unlikely to be causally linked with CRP concentrations/activity." (PMID 31563954, 2019). "None of the CRP rs1417938, rs1800947, rs1205 variants was associated with schizophrenia." (PMID 30190688, 2018). "WBC was within normal levels; however, there was a trend toward WBC being higher in the elevated CRP group compared to the normal CRP group, which is consistent with findings from a recent study that reported a positive relationship between leukocytes and CRP in 213 patients with schizophrenia." (PMID 30364161, 2018). "On average, the chronically ill patients with schizophrenia displayed significantly lower CRP levels than the acute psychosis group, supporting previous work showing that CRP may decrease following antipsychotic treatment and resolution of acute psychotic episodes." (PMID 30364161, 2018). "Notably, elevated CRP levels have been reported in schizophrenia by multiple research groups." (PMID 28396623, 2017). "Analyses of (a) schizophrenia compared to (c) no psychosis excluded participants with non-schizophrenia non-affective psychosis from the comparison group and did not alter the results of the association between CRP and schizophrenia." (PMID 27622678, 2017). "Taken together, these results show that CRP is highly unlikely to contribute causally to most of the major common somatic and neuropsychiatric outcomes that were investigated in the present study, with the possible exception of schizophrenia." (PMID 27327646, 2016). "Chronic low-grade systemic inflammation is frequently observed in patients with schizophrenia, with elevated levels of inflammatory cytokines such as interleukin-6 (IL-6), tumor necrosis factor-alpha (TNF-α), and C-reactive protein (CRP)." (PMID 40786633, 2025). "The aim of this study was to determine the interrelations between family support, C-reactive protein (CRP) and Body Mass Index (BMI) in a sample of outpatients with schizophrenia." (PMID 40724779, 2025). "Evidence-based studies are representative of altered levels of inflammatory cytokines, including C-reactive protein, IL-1, IL-6, and TNF-α in schizophrenia patients, which affect the basal ganglia and induce negative symptoms." (PMID 39716387, 2024). "An association has been observed between the inflammatory state measured by C-reactive Protein (CRP) and cytokine levels in peripheral blood and cognitive impairment in patients with schizophrenia and BD." (PMID 38758506, 2024).
schizophrenia (continued). "MoCA scores were lower, and levels of NLR, MLR, PLR, SII, CRP, ESR, and CIMT were higher in schizophrenia compared to the HC group (respectively; p < 0.001, p < 0.001, p = 0.035, p = 0.008, p = 0.002, p < 0.001, p < 0.001, p < 0.001)." (PMID 37763110, 2023). "In this study, higher levels of NLR, MLR, PLR, SII, CRP, and ESR markers in schizophrenia patients compared to the control group indicate inflammation." (PMID 37763110, 2023). "These methods can potentially validate the function of markers such as LMR, NLR, CRP, and cytokines, among others, in the etiology of CLB in schizophrenia." (PMID 37821904, 2023). "In this study, NLR, MLR, PLR, SII, CRP, and ESR markers were higher in schizophrenia compared to HC, indicating inflammation." (PMID 37763110, 2023). "In schizophrenia, NLR was correlated with C Reactive Protein (CRP) and OS parameters, but the amount of evidence is still less confidently supportive of this conclusion." (PMID 37824542, 2023). "Abnormal levels of inflammatory factors including C-reactive protein, transforming growth factor α(TGF- α), interleukin-6 (IL-6) and insulin-like growth factor (IGF-I) in schizophrenia were confirmed in the observational and MR studies." (PMID 37743466, 2023). "CRP and CAR levels were higher in schizophrenia patients who committed murder in the first degree than in patients who committed other crimes." (PMID 36983657, 2023). "To explore this, we measured suPAR, CRP, TNF, sTNFR1 and IL-6 in plasma obtained before and after a 12-week exercise intervention RCT in individuals with schizophrenia." (PMID 37265560, 2023). "Inflammatory parameters such as NLR, MLR, PLR, CRP, and ESR were found to be higher in the schizophrenia group." (PMID 37763110, 2023). "A positive correlation between CRP and PANSS P scale and MDA and PANSS P scale may indicate a significant relationship between the development of low-grade inflammation and damage associated with oxidative stress in the development of the first symptoms of schizophrenia." (PMID 35566680, 2022). "In the present study, we recruited a relatively larger sample of patients with schizophrenia and measured more plasma inflammatory cytokines, including IL-1β, IL-2, IL-4, IL-6, IL-8, IL-10, IL-12, IL-17, TNF-α, IFN-γ, and CRP." (PMID 36341400, 2022). "A positive correlation between CRP and PANSS P scale and MDA and PANSS P scale may indicate a significant relationship between the development of low-grade inflammation and cell damage associated with oxidative stress in the development of the first symptoms of schizophrenia." (PMID 35566680, 2022). "A few studies have investigated the role of C-reactive protein (CRP), an acute phase protein synthesized by the liver that can be induced by cytokines, and has been shown to be elevated in patients with schizophrenia in multiple meta-analyses." (PMID 32153436, 2020). "They found that soluble CD14 was more prevalent in patients with schizophrenia and both sCD14 and LBP correlated with CRP in that group." (PMID 30374300, 2018). "The present study detected significant association between measures of functional impairment and markers of inflammation, especially elevated CRP in a group of stable outpatients with DSM-IV and ICD10 diagnosis of schizophrenia." (PMID 27547191, 2016). "CRP levels can be increased by infection and/or inflammation, so taken together, these results suggest that a peripheral stimulus, perhaps viral and/or bacterial, may activate the co-expression module related to immune/inflammation responses in the CP of patients with schizophrenia." (PMID 27898074, 2016). "The statins are also known to decrease C-reactive protein (CRP), which has been shown in an SMRI-funded study to be elevated in schizophrenia." (PMID 23782463, 2013).
schizophrenia (continued). "Elevated HERV-W env expression in individuals with schizophrenia correlates with proinflammatory cytokines, and downregulation of IL-6 in SH-SY5Y cells inhibits HERV-W env-induced C-reactive protein(CRP) expression." (PMID 41200560, 2025). "The apparent LBP elevation was not schizophrenia‐specific; its strong correlations with CRP and neutrophils point to smoking related inflammation rather than a schizophrenia specific effect." (PMID 41084047, 2025). "Studies on schizophrenia have also discovered a negative correlation between CRP (C-reactive protein, CRP) levels and cognitive function in individuals with schizophrenia." (PMID 40291517, 2025). "In agreement with other studies with participants from the general population and among patients with schizophrenia, obese participants in this study were significantly more likely to have positive CRP values compared to non-obese individuals." (PMID 40724779, 2025). "C-reactive protein (CRP) is a non-specific marker of the inflammatory process, and studies have shown that CRP levels are higher during the onset period of schizophrenia, but normal in non-psychotic states." (PMID 37728803, 2024). "In particular, few studies have investigated the impact of SFN on oxidative stress and C-reactive protein (CRP) levels in schizophrenia patients showing improvement in negative symptoms." (PMID 37728803, 2024). "PUFAs reduce neuroinflammation and, in patients with schizophrenia, result in a reduction in proinflammatory cytokines, such as IL-6 and TNF-α; a reduction in CRP; and an increase in BDNF, which, due to its neurotrophic action, has positive effects on cognition function." (PMID 37371435, 2023). "Additionally, our previous research suggested that CRP, IL10, and BDNF, which are regulated by ERVW-1, can be used as serum biomarkers of schizophrenia." (PMID 37376599, 2023). "In a later lifestyle modification study in obese, non-diabetic individuals with schizophrenia, Kuo and co-workers were not able to detect significant decrease of either CRP, TNF or IL-6 after 10 weeks of intervention." (PMID 37265560, 2023). "CRP and CAR were found to be higher in the group with more aggression in a study that looked at the relationship between impulsivity, aggression, and inflammation in schizophrenia patients." (PMID 36983657, 2023). "Furthermore, evidence shows that individuals with high levels of C-reactive protein (CRP), a biomarker of chronic or acute inflammation, were more likely to develop schizophrenia." (PMID 36313375, 2022). "Multivariable models that conditioned CRP effects on interleukin-6 signaling and body mass index supported that the CRP-schizophrenia relationship was not driven by these factors." (PMID 35385317, 2022). "Among biomarkers of inflammation potentially contributing to the development of cognitive impairment in schizophrenia, the evidence is more robust for CRP, with only a few studies that do not support this conclusion." (PMID 35873262, 2022). "In the case of schizophrenia, high peripheral CRP is correlated with negative symptoms as well as cortical thinning in frontal, insula and temporal regions." (PMID 36075890, 2022). "The cytokines that change in schizophrenia have similar changes in metabolic disorders, such as interleukin-1Rα(IL-1Rα), IL-1β, IL-2, IL-6, IL-10, interferon-γ(IFN-γ), tumor necrosis factor-α(TNF-α), and C-reactive protein (CRP)." (PMID 35135531, 2022). "This study aimed to compare the differences in cognitive functioning and plasma levels of C-reactive protein (CRP) and inflammatory cytokines among DS patients, nondeficit schizophrenia (NDS) patients, and healthy controls (HCs)." (PMID 36341400, 2022). "We also investigated markers of inflammatory response (C-reactive protein, IL-2, IL-6, IL-10), the activity of leukocytic elastase (LE) and α1-proteinase inhibitor (a1-PI), antibodies to S100B and myelin basic protein (MBP) in schizophrenia." (PMID 34025476, 2021).